IL6 (interleukin 6)
Diseases named in the same sentence as IL6 in open-access papers (continued):
Sharing a sentence is not in itself a finding about the gene and the disease.
tumor (continued). "In human CRC, F. nucleatum group infection promotes M2-type macrophage polarization and tumor growth and progression in a TLR4-dependent manner by activating the IL-6/p-STAT3/c-MYC and the TLR4/NF-ĸB/S100A9 signaling pathways." (PMID 41471188, 2025). "Pro-tumor effects: Chronic STING signaling induces PD-L1/IDO upregulation and NF-κB-driven IL-6 production." (PMID 41573551, 2025). "For example, in the B16.F10 murine melanoma model, TLR2 agonists stimulate the release of MC-derived interleukin-6 and CCL3, which directly inhibit tumor growth and indirectly facilitate the recruitment of natural killer cells (NKs)." (PMID 41425713, 2025). "Further studies have shown that TAMs induce PD-L1 expression in gastric cancer cells through IL-6 and TNF-α signaling, thereby helping tumor cells evade cytotoxic T cell killing." (PMID 41041337, 2025). "Known effects of endurance exercise that can reduce tumor growth include a reduction in C-reactive protein (CRP) levels and the release of inflammatory markers such as IL-6, sex hormones, insulin response, and vascularization." (PMID 40362215, 2025). "For example, tumor cells recruit and secrete growth factors such as TGF-β, platelet-derived growth factor (PDGF), and IL-6, which stimulate fibroblasts to transform into CAFs." (PMID 41236411, 2025). "Upregulation of miR-125a and let-7e, which target IL-6, the IL-6 receptor, and STAT3, exerts anti-VM effects and sensitizes tumor cells to chemotherapy." (PMID 41400702, 2025). "For instance, activation of TLR4 can promote the secretion of pro‐inflammatory cytokines and chemokines, such as IL‐6, IL‐10, and TNF‐α, which can create an immunosuppressive microenvironment that facilitates tumour growth and metastasis." (PMID 40696496, 2025). "Increased levels of cytokines such as IL-6, IL-8, and TGF-β promote EGFR TKI resistance and tumor progression." (PMID 40002883, 2025). "Activated fibroblasts can secrete more cytokines such as MMP-2, TGF-β, SDF-1, and IL-6 for extracellular matrix (ECM) remodeling and tumor progression." (PMID 40707430, 2025). "M2d macrophages, recently identified as tumor-associated macrophages, are induced by TLR ligands or IL-6 and secrete IL-10 and vascular endothelial growth factor (VEGF), promoting tumor vessel formation and metastasis." (PMID 40760449, 2025). "One is the classically activated M1-like macrophage, which promotes an anti-tumor immune response through the production of pro-inflammatory cytokines such as IL-12, IL-1, IL-6, and tumor necrosis factor (TNF)-α, thereby exerting tumor-suppressive effects." (PMID 40028336, 2025). "CAFs, a key component of the TME, secrete a range of cytokines—including TGF‐β, ILs (IL‐2, IL‐6), chemokines (CXCL2, CXCL5, CXCL12), and FGF7—to support tumor cell proliferation." (PMID 41164803, 2025). "In the TME, the IL-6/JAK/STAT3 signaling can drive the proliferation, survival, invasion, and metastasis of tumor cells and strongly suppress the anti-tumor immune response." (PMID 40568576, 2025). "Cytokine analysis revealed high concentrations (>10 ng/mL) of IL-1, IL-6, IP-10, MCP-1, and VEGF, suggesting that tumor, stromal, or circulating cells in MPE contribute to shaping the culture environment." (PMID 40004228, 2025). "These macrophages secrete proinflammatory and protumorigenic mediators, such as IL‐6, TNF‐α, and TGF‐β, which not only promote tumor cell proliferation and metastasis but also inhibit the effector functions of CD8+ T cells." (PMID 41267926, 2025). "This modality additionally amplifies proinflammatory cytokine secretion (notably IL-6 and TNF-α) that cooperates with ICIs to intensify T cell-dependent anti-tumor activity." (PMID 40445365, 2025). "Our results revealed a predominantly pro-inflammatory tumor microenvironment, driven by cytokines such as CXCL8, IL-6, and TNF-α, which create a favorable niche for tumor growth." (PMID 40895532, 2025).
tumor (continued). "Preclinical studies in EC models suggest that targeting FAP (e.g., with inhibitory antibodies or small molecules) or blocking IL-6 signaling can inhibit CAF activity, reduce tumor growth, and sensitize tumors to chemotherapy." (PMID 40746533, 2025). "LYZ activates macrophages to kill tumors and plays a role in tumor suppression; however, under chronic inflammation, LYZ releases proinflammatory factors (IL-6, TNF-α) to promote immunosuppression in the tumor microenvironment." (PMID 41384115, 2025). "Second, blood loss promotes systemic release of pro-inflammatory cytokines including IL-6 and TNF-α, establishing a chronic inflammatory environment conducive to tumor proliferation and metastasis." (PMID 41019554, 2025). "These inflammatory cells release interleukin-6 (IL-6), tumor necrosis factor-α (TNF-α) in tumor tissues, which activate multiple signaling pathways to promote tumor cell proliferation, survival, invasion and metastasis." (PMID 41256327, 2025). "Elevated levels of inflammatory cytokines such as IL-6 and TNF-α not only promote tumor growth but also suppress effective anti-tumor immune responses." (PMID 40028339, 2025). "Elevated levels of pro-inflammatory cytokines such as IL6 and TNF-α, along with senescent cell accumulation, foster a tumor-permissive microenvironment." (PMID 40781676, 2025). "Tumor-derived inflammatory cytokines, including IL-6, IL-1β, IL-8, GM-CSF, and VEGF, support the expansion, survival, and migration of MDSCs to the tumor site, establishing a chronic state of immune suppression." (PMID 40475782, 2025). "SASP components, including IL-6, IL-8, TNF-α, and MMPs, are secreted in tumor microenvironments and can be detected in blood or saliva samples." (PMID 41463272, 2025). "CAFs not only increase tumour progression through the secretion of protumour factors, such as VEGF and IL-6, but also induce vasculogenic mimicry (VM), which accelerates metastasis in gallbladder cancer." (PMID 40861435, 2025). "The tumor microenvironment (TME) is inherently inflammatory, driven by persistent production of pro-inflammatory cytokines (e.g., IL-6, IL-1β, TNF-α), chemokines, ROS, and activation of transcription factors such as NF-κB and STAT3." (PMID 41020838, 2025). "To evaluate the effects of oral probiotics CB and AKK on the immune response in 4 T1 tumor‐bearing mice, we measured the changes in levels of tumor necrosis factor (TNF‐α), IL‐6, and IL‐10 in both the tumors and serum of the mice." (PMID 40497373, 2025). "Malignant tumor cells exploit this mechanism by secreting cytokines such as prostaglandin E2 (PGE2), interleukin-6 (IL-6), and parathyroid hormone-related peptide (PTHrP)." (PMID 40426987, 2025). "Studies have shown that cytokines such as IL‐6 and TNF‐α play key roles in the tumor microenvironment in the context of elevated cytokines and bone metastasis progression." (PMID 40040540, 2025). "Evidence suggests that combined blockade of IL-6 and PD-1 can restore CD8+ T cell effector function, thereby enhancing antitumor immunity and suppressing tumor growth." (PMID 41254689, 2025). "CAFs promote tumor growth and metastasis by secreting immune-suppressive factors (e.g., IL-6, TGF-β, CXCL12) and by altering the physical properties of the tumor stroma." (PMID 40038745, 2025). "IDO1 promotes IL-6, which enhances MDSC generation and migration into tumor tissues, creating an immunosuppressive microenvironment." (PMID 41035912, 2025). "Using next‐generation sequencing, we found that in tumor tissues with high CCL24 expression, iCAF markers (IL1A, IL1B, IL6, CXCL1, and CXCL5) were significantly highly expressed, indicating high infiltration of iCAFs in the TME." (PMID 40397411, 2025). "Like IL-6, TNF-α contributes to tumorigenesis by promoting cell proliferation, angiogenesis, metastasis, and even participating in the early stages of tumor initiation." (PMID 41267807, 2025).
tumor (continued). "Specifically in this experiment, SB demonstrated the ability to decrease the blood concentration of tumor specific markers such as CEA, TNF-alpha, IL-6 and liver function markers (including ALT and AST) in the treated groups." (PMID 40712409, 2025). "In addition, the reduction of adipose tissue may also affect the release of inflammatory factors such as interleukin-6 and tumor necrosis factor-α, thus improving the metabolic state of the body and the tumor microenvironment and increasing the sensitivity of treatment." (PMID 40904512, 2025). "Conversely, introduction an antisense targeting 5′‐half‐GlyGCC to tumour Te‐EVs abrogated p65 phosphorylation and reduced TNF‐α and IL‐6 secretion in dTHP‐1 cells via TLR8." (PMID 40326665, 2025). "In particular, IFIT3 enhances NF-κB activity, which subsequently promotes the secretion of inflammatory mediators such as IL-6, TNF-α, and COX-2, driving tumor cell proliferation, resistance to apoptosis, and angiogenesis." (PMID 40061935, 2025). "In rectal cancer, post-neoadjuvant therapy SASP factors such as IL6, IL8, and CCL5 were correlated with increased CD8 + T-cell infiltration and improved tumor regression." (PMID 40781676, 2025). "In vivo, S1-driven tumor suppression correlated with significant remodeling of the tumor microenvironment, marked by reduced levels of immunosuppressive cytokines (TGF-β, IL-6, IL-10) and increased infiltration of TAMs." (PMID 40507880, 2025). "M1-type macrophages are induced by Th1 cytokines and are responsible for the presentation of tumor-specific antigens and the release of pro-inflammatory cytokines (e.g., IL-1, IL-6, and TNF-α) to augment the anti-tumor immune response." (PMID 39975599, 2025). "Given theconstitutive activity of the IL-6/JAK2/STAT3 signaling pathway in malignantdiseases, resistance to ferroptosismay be considered a necessary condition for tumor progression." (PMID 40264585, 2025). "By producing TGF-β, IL-6, CXCL12, and MMPs, CAFs induce EMT and modify the ECM, enhancing tumour invasiveness while creating a stiffened, collagen-rich matrix." (PMID 40361472, 2025). "Pro-tumorigenic cytokines include IL-6, TGF-β, vascular endothelial growth factor (VEGF), and IL-10, while anti-tumor cytokines include IFN-γ, tumor necrosis factor-α (TNF-α), and IL-12." (PMID 40227644, 2025). "Tumor–derived exosomes and soluble mediators such as osteopontin (OPN) and IL-6 reprogram infiltrating neutrophils and macrophages into pro-tumoral phenotypes." (PMID 41614820, 2025). "A decrease in key inflammatory biomarker (such as IL-6, TNF-α, IFN-γ, etc.)levels can reshape the tumor immune microenvironment." (PMID 40429988, 2025). "Overexpression of miR-217 reduces IL-6 levels, which in turn inhibits the JAK2/STAT3 pathway, decreasing M2 macrophage markers and promoting an immune environment less conducive to tumor progression." (PMID 40330466, 2025). "scRNA-seq revealed compartment-specific target localization: AKT1/ESR1 in tumor cells, SRC/IL6 in myeloid cells, and MTOR/HIF1A across stromal compartments." (PMID 40746726, 2025). "M1 macrophages play a pivotal role in innate host defense and tumor cell eradication by generating reactive oxygen/nitrogen species (ROS/RNS) and pro-inflammatory cytokines such as IL-1β, IL-6, and tumor necrosis factor-α (TNF-α)." (PMID 40746825, 2025). "CAFs are key stromal components known to secrete TGF-β and IL-6, remodel the ECM, and promote immune suppression and tumor invasion." (PMID 40843374, 2025). "Adipocytes themselves, together with immune cells such as macrophages, regulate the inflammatory status of the adipose‐rich TME by releasing inflammatory factors such as IL‐1, IL‐6 and TNF‐α, all of which benefit tumor progression." (PMID 39496581, 2025). "These M2-like TAMs secrete factors such as interleukin-6 (IL-6), which in turn activate anti-apoptotic pathways, including STAT3, within tumor cells." (PMID 41573644, 2025).
tumor (continued). "TNF-α and IL-6 are key inflammatory cytokines involved in immune suppression and tumorigenesis in CRC, providing growth and expansion signals to tumor progenitor cells and enhancing CRC development." (PMID 41200195, 2025). "Tumor-derived factors, particularly Activin A (a TGF-β family cytokine) and IL-6, induce the expression of Noggin, a soluble BMP inhibitor, in the muscle tissue." (PMID 40869331, 2025). "Thus, it has been experimentally confirmed that thepro-inflammatory cytokine IL-6 blocks ferroptosis by activating the xC-system.Involvement of intratumoral immunosuppression in the blocking of ferroptosishas also been confirmed in subcutaneous tumor xenograft mouse models." (PMID 40264585, 2025). "The tumor microenvironment, driven by factors such as TGF-β, IL-6, and hypoxia, orchestrates this polarization, profoundly influencing disease progression and therapeutic outcomes." (PMID 40486616, 2025). "Several secretory factors such as cytokines (IL-6, IL-10 and IL-11, IL-12, GM-CSF and TNF-α), chemokines CXCL-8, CXCL-10, CXCL12 and CCL-3 and growth factors VEGF and TGF-β are important roles in tumor cell invasion and infiltration." (PMID 41155765, 2025). "Accordingly, these cells produce high levels of pro-inflammatory cytokines, such as TNF, IL-1β, IL-6, IL-12, IL-23, and CCL2, to promote immune responses against bacteria, intracellular pathogens, and tumor cells." (PMID 40109347, 2025). "Elevated cytokine levels, including IL1α, TNFα, IL6, IL10, IL17, and IL12, represent the rejuvenation of tumor immunity in response to combination ICI." (PMID 40313772, 2025). "For example, IL6 secreted by CAFs activates the STAT3 signaling pathway in cancer cells and macrophages, enhancing pro-inflammatory properties and suppressing anti-tumor immune responses." (PMID 41050676, 2025). "Pro-inflammatory cytokines such as IL-6 and TNF-α often dominate the microenvironment, promoting tumor proliferation and facilitating immune evasion." (PMID 40352941, 2025). "The analysis of factors affecting microbiota-brain axis relationships through regression methods showed that CRP and IL-6 and TNF-α inflammatory markers and tumor size and disease stage and hospital stay duration had positive effects." (PMID 41451009, 2025). "This dual activation/suppression pattern suggests evolved immune evasion through macrophage-driven chronic inflammation (IL-6/IL-1β axis) and PD-1/STAT1-mediated TIL exhaustion, while compromised antiviral responses facilitate tumor immunoediting." (PMID 40697520, 2025). "Analysis of the TCGA database revealed significantly higher expression of IL6 and IL11 in CRC tumor tissues compared with adjacent normal samples." (PMID 41585878, 2025). "In turn, activated CAFs secrete exosomes and soluble factors such as IL-6, CXCL12, and WNT-ligands, which induce JAK/STAT3 signaling in tumor cells and an enhanced PD-L1 expression, supporting immune evasion." (PMID 41439998, 2025). "IL-6 has a dual role: intratumorally, it can suppress CD8+ T cell-mediated tumor cytotoxicity and promote tumor cell proliferation, whereas systemically, it is essential for T cell priming and migration." (PMID 40386779, 2025). "Cardamonin reduced pro-tumor activity of TAMs, decreased M2 markers (CD163, CD206), and suppressed IL-6, VEGFα, MMP2, MMP9 secretion." (PMID 40330466, 2025). "TAMs are recruited by hypoxic conditions, necrosis, and tumor-derived cytokines such as CSF1 and IL-6." (PMID 40872551, 2025). "Meanwhile, MSL was demonstrated to significantly ameliorate the tumor inflammatory microenvironment by inhibiting pro-inflammatory factors (e.g., TNF-α, IL-6)." (PMID 40528838, 2025). "DTP cells also actively reshape the tumor microenvironment (TME) by secreting IL-6, TGF-β, and CXCL12, which recruit immunosuppressive cells (e.g., TAMs, Tregs), thereby reinforcing drug tolerance and promoting tumor recurrence." (PMID 40894234, 2025).
tumor (continued). "TPTEP1 suppresses the progression of HCC cells by affecting the IL-6/STAT3 signaling pathway, revealing its tumor-suppressive role in HCC chemotherapy." (PMID 40352941, 2025). "Synergistically, these perturbations activate NF-κB/STAT3 signaling, generating a pro-inflammatory cytokine milieu (IL-6, TNF-α, IL-1β) that promotes tumor progression through autocrine-paracrine cascades." (PMID 40919140, 2025). "The increased IL‐6, in turn, elevates EIF4A3 and CCL2 levels within tumor cells, which upregulate circSERPINE2 biogenesis in tumor cells and promote the recruitment of TAMs in a positive feedback mechanism." (PMID 39901896, 2025). "A central molecular mechanism involves the suppression of the NF-κB signaling pathway, leading to reduced expression of TNF-α and IL-6, thereby lowering inflammation in the TME and inhibiting tumor growth and metastasis." (PMID 41480347, 2025). "The release of pro-inflammatory chemokines and cytokines, such as IL-1, IL-2, IL-6, CCL-2, CCL-8, TNF-α and TGF-β, facilitate the recruitment of brain-resident immune cells to the tumour site." (PMID 41301734, 2025). "Tumor cells and HPV-infected dysplastic cells release cytokines such as IL-6 and granulocyte colony-stimulating factor, driving up platelet production while also inducing an immunosuppressive milieu that reduces lymphocyte counts." (PMID 40566623, 2025). "They found that neutralizing IL-6 prevented the selectin and Intercellular adhesion molecule-1 (ICAM-1) – dependent migration of adoptively transferred CD8+ T cells through the tumor vasculature." (PMID 40092992, 2025). "The core of this loop, driven by IL-6, TNF-α, and IL-8, directly promotes tumor cell survival, proliferation, and invasion, while also inducing angiogenesis, thereby facilitating tumor metastasis." (PMID 41394847, 2025). "Key cytokines such as interleukin-6 (IL-6), tumor necrosis factor-alpha (TNF-α), interleukin-1 beta (IL-1β), and interferon-gamma (IFN-γ) are critical mediators of tumor progression, immune tolerance, and therapy resistance." (PMID 41401147, 2025). "The apoptosis rate of A549 cells in the combined IL-6 and PD1 blocked group was significantly increased; thus, indicating that the tumor cell killing function of CD8+T cells was enhanced." (PMID 40040705, 2025). "Conversely, iCAFs secrete inflammatory cytokines like IL-6 and CXCL12, driving tumor cell proliferation, angiogenesis, and immune escape." (PMID 40177538, 2025). "Specifically, IL-6 activates the STAT3 signaling pathway, leading to anti-apoptotic effects and promoting cell proliferation, thereby enabling sustained tumor growth by evading cell death." (PMID 41294748, 2025). "Chronic P.g. infection increases IL-6 secretion via TLR signaling, which activates STAT1 and STAT3, driving tumor progression through a feedback loop involving CXCL10, PD-L1, and GAS6 genes." (PMID 40924302, 2025). "Enhanced m6A methylation stabilizes IL-6 mRNA, increasing its expression in the HCC microenvironment, which promotes tumor cell proliferation and survival." (PMID 40034695, 2025). "Hypoxia itself promotes cytokine production, and IL-6 can further amplify the hypoxic response via STAT3 and HIF-1α stabilization, forming a detrimental positive feedback loop that exacerbates tumor progression." (PMID 41302515, 2025). "Recent studies have confirmed that relevant fungal components (mycobiome) activate the IL-1β/IL-6/IL-23–Th17 axis via receptors such as Dectin-1/TLR2/4, thereby shaping a pro-tumour inflammatory microenvironment." (PMID 41321823, 2025). "Through interactions among tumor cells, stromal components, ECM, soluble mediators such as VEGF, IL-6, and GM-CSF, the TME provides survival signals that promote environment-mediated drug resistance (EM-DR)." (PMID 41614820, 2025). "Evaluation of macrophage activating cytokines showed that GB2 treatment indeed led to a significant upregulation of IL-6, TNF-α, and CXCL10 both in tumor and serum." (PMID 39744236, 2025).